ATOSA (atos homolog A)
Description:
Transcription regulator that syncronizes transcriptional and translational programs to promote macrophage invasion of tissues.
Synonyms: FAM214A; KIAA1370; FLJ10980
Tractability: PROTAC: ubiquitination databases record sites on it.
Gene: Protein-coding gene on chromosome 15 (52,581,317 to 52,709,817, reverse strand). Ensembl gene ENSG00000047346.
Subcellular location: Nucleus
Subcellular location (Human Protein Atlas): Nucleoplasm
Gene Ontology:
Molecular function: protein binding
Cellular component: nucleus
Genetic constraint (gnomAD): Loss-of-function variants: 50 observed, 99.78 expected, observed/expected ratio (o/e) 0.5, 90% interval 0.4 to 0.63. The upper end of that interval is the gene's LOEUF score, 0.63, which puts it in group 2 of 6, group 1 being the genes least tolerant of losing a copy. Missense variants: 1,128 observed, 1,217.9 expected, observed/expected ratio (o/e) 0.93, 90% interval 0.88 to 0.97. Synonymous variants: 402 observed, 418.82 expected, observed/expected ratio (o/e) 0.96, 90% interval 0.88 to 1.04.
Homologues: Orthologues: chimpanzee ATOSA (99% identical), macaque ATOSA (97% identical), rabbit ATOSA (85% identical), dog ATOSA (85% identical), pig ATOSA (85% identical), rat Atosa (75% identical), mouse Atosa (74% identical), guinea pig ATOSA (71% identical), tropical clawed frog atosa (52% identical), zebrafish atosa (46% identical). Paralogues in human: ATOSB (15% identical).
Diseases named in the same sentence as ATOSA in open-access papers:
ATOSA is named in the same sentence as 9 diseases in open-access papers, as found by Europe PMC text mining. Sharing a sentence is not in itself a finding about the gene and the disease. The quoted sentences say what the papers report.
neurodegenerative disease (1 paper, 2022). A disorder of the central nervous system characterized by gradual and progressive loss of neural tissue and neurologic function. "Many neurodegenerative diseases are connected to defects in OxPhos or PGC‐1; examining if mutating AtosA in neurons results in lower levels of mitochondrial OxPhos, and decreased neural survival and signaling will be an interesting area of inquiry." (PMID 35319107, 2022).
ATOSA also shares sentences with these, for which no sentence is quoted: breast carcinoma (2 papers); cholestasis (1); mood disorder (1); Obesity (1); pancreatic cancer (1); phospholipidosis (1); Sepsis (1); uterine cancer (1).